TM2D2 (TM2 domain containing 2)
Synonyms: BLP1
Tractability: Antibody: UniProt predicts a signal peptide or a membrane-spanning region; the Human Protein Atlas places it where antibodies can reach. PROTAC: its protein half-life has been measured.
Gene: Protein-coding gene on chromosome 8 (38,988,808 to 38,996,824, reverse strand). Ensembl gene ENSG00000169490.
Subcellular location: Membrane
Subcellular location (Human Protein Atlas): Nucleoplasm; Plasma membrane; Vesicles
Gene Ontology:
Molecular function: protein binding
Cellular component: membrane
Genetic constraint (gnomAD): Loss-of-function variants: 15 observed, 17.8 expected, observed/expected ratio (o/e) 0.84, 90% interval 0.56 to 1.3. The upper end of that interval is the gene's LOEUF score, 1.3, which puts it in group 5 of 6, group 1 being the genes least tolerant of losing a copy. Missense variants: 213 observed, 240.99 expected, observed/expected ratio (o/e) 0.88, 90% interval 0.79 to 0.99. Synonymous variants: 109 observed, 103.83 expected, observed/expected ratio (o/e) 1.05, 90% interval 0.9 to 1.23.
Homologues: Orthologues: chimpanzee TM2D2 (100% identical), macaque TM2D2 (99% identical), dog TM2D2 (96% identical), pig TM2D2 (95% identical), guinea pig TM2D2 (92% identical), rabbit TM2D2 (92% identical), mouse Tm2d2 (90% identical), rat Tm2d2 (90% identical), zebrafish tm2d2 (69% identical), tropical clawed frog tm2d2 (67% identical), Drosophila melanogaster amrt (44% identical), Caenorhabditis elegans C02F5.13 (40% identical). Paralogues in human: TM2D3 (27% identical), TM2D1 (25% identical).
Diseases named in the same sentence as TM2D2 in open-access papers:
TM2D2 is named in the same sentence as 6 diseases in open-access papers, as found by Europe PMC text mining. Sharing a sentence is not in itself a finding about the gene and the disease.
TM2D2 shares sentences with these, for which no sentence is quoted: infection (2 papers); cancer (1); infectious disease (1); mental retardation (1); metabolic disorder (1); neurological disorders (1).